POLR2B (RNA polymerase II subunit B)
Description:
Catalytic core component of RNA polymerase II (Pol II), a DNA-dependent RNA polymerase which synthesizes mRNA precursors and many functional non-coding RNAs using the four ribonucleoside triphosphates as substrates (By similarity). Pol II-mediated transcription cycle proceeds through transcription initiation, transcription elongation and transcription termination stages. During transcription initiation, Pol II pre-initiation complex (PIC) is recruited to DNA promoters, with focused-type promoters containing either the initiator (Inr) element, or the TATA-box found in cell-type specific genes and dispersed-type promoters that often contain hypomethylated CpG islands usually found in housekeeping genes. Once the polymerase has escaped from the promoter it enters the elongation phase during which RNA is actively polymerized, based on complementarity with the template DNA strand. Transcription termination involves the release of the RNA transcript and polymerase from the DNA. Forms Pol II active center together with the largest subunit POLR2A/RPB1. Appends one nucleotide at a time to the 3' end of the nascent RNA, with POLR2A/RPB1 most likely contributing a Mg(2+)- coordinating DxDGD motif and POLR2B/RPB2 participating in the coordination of a second Mg(2+) ion and providing lysine residues believed to facilitate Watson-Crick base pairing between the incoming nucleotide and template base. Typically, Mg(2+) ions direct a 5' nucleoside triphosphate to form a phosphodiester bond with the 3' hydroxyl of the preceding nucleotide of the nascent RNA, with the elimination of pyrophosphate. The reversible pyrophosphorolysis can occur at high pyrophosphate concentrations (By similarity). Can proofread the nascent RNA transcript by means of a 3' -> 5' exonuclease activity. If a ribonucleotide is mis-incorporated, backtracks along the template DNA and cleaves the phosphodiester bond releasing the mis-incorporated 5'-ribonucleotide (By similarity). RNA-dependent RNA polymerase that catalyzes the extension of a non-coding RNA (ncRNA) at the 3'-end using the four ribonucleoside triphosphates as substrates. An internal ncRNA sequence near the 3'-end serves as a template in a single-round Pol II-mediated RNA polymerization reaction. May decrease the stability of ncRNAs that repress Pol II-mediated gene transcription.
Synonyms: RPB2; POL2RB; hRPB140
Tractability: Small molecule: a structure with a bound ligand is known. PROTAC: ubiquitination databases record sites on it; its protein half-life has been measured.
Target class: Enzyme; Transferase
Gene: Protein-coding gene on chromosome 4 (56,977,722 to 57,031,158, forward strand). Ensembl gene ENSG00000047315.
Subcellular location: Nucleus
Subcellular location (Human Protein Atlas): Nucleoplasm
Pathways (Reactome):
Disease: Abortive elongation of HIV-1 transcript in the absence of Tat; Dengue Virus-Host Interactions; Formation of HIV elongation complex in the absence of HIV Tat; Formation of HIV-1 elongation complex containing HIV-1 Tat; Formation of the HIV-1 Early Elongation Complex; HIV Transcription Initiation; HIV elongation arrest and recovery; Pausing and recovery of HIV elongation; Pausing and recovery of Tat-mediated HIV elongation; RNA Pol II CTD phosphorylation and interaction with CE during HIV infection; RNA Polymerase II HIV Promoter Escape; Signaling by FGFR2 IIIa TM; Tat-mediated HIV elongation arrest and recovery; Tat-mediated elongation of the HIV-1 transcript; Transcription of the HIV genome; Viral Messenger RNA Synthesis
Gene expression (Transcription): Formation of RNA Pol II elongation complex; Formation of the Early Elongation Complex; MicroRNA (miRNA) biogenesis; PIWI-interacting RNA (piRNA) biogenesis; RNA Pol II CTD phosphorylation and interaction with CE; RNA Polymerase II Pre-transcription Events; RNA Polymerase II Promoter Escape; RNA Polymerase II Transcription Elongation; RNA Polymerase II Transcription Initiation; RNA Polymerase II Transcription Initiation And Promoter Clearance; RNA Polymerase II Transcription Pre-Initiation And Promoter Opening; RNA polymerase II transcribes snRNA genes; Transcriptional regulation by small RNAs
Metabolism of RNA: Processing of Capped Intron-Containing Pre-mRNA; mRNA Capping; mRNA Polyadenylation; mRNA Splicing - Major Pathway; mRNA Splicing - Minor Pathway
DNA Repair: Dual incision in TC-NER; Formation of TC-NER Pre-Incision Complex; Gap-filling DNA repair synthesis and ligation in TC-NER; Transcription-Coupled Nucleotide Excision Repair (TC-NER)
Signal Transduction: Estrogen-dependent gene expression
and 3 more pathways
Gene Ontology:
Molecular function: 5'-3' RNA polymerase activity; DNA-directed RNA polymerase activity; protein binding; RNA binding; RNA-directed RNA polymerase activity; DNA binding; chromatin binding; ribonucleoside binding
Biological process: transcription by RNA polymerase II; transcription elongation by RNA polymerase II; transcription initiation at RNA polymerase II promoter; DNA-templated transcription elongation; DNA-templated transcription; RNA-templated transcription
Cellular component: chromosome, telomeric region; membrane; nucleoplasm; nucleus; RNA polymerase II, core complex
Genetic constraint (gnomAD): Loss-of-function variants: 27 observed, 65.51 expected, observed/expected ratio (o/e) 0.41, 90% interval 0.3 to 0.57. The upper end of that interval is the gene's LOEUF score, 0.57, which puts it in group 2 of 6, group 1 being the genes least tolerant of losing a copy. Missense variants: 303 observed, 806.1 expected, observed/expected ratio (o/e) 0.38, 90% interval 0.34 to 0.41. Synonymous variants: 248 observed, 271.35 expected, observed/expected ratio (o/e) 0.91, 90% interval 0.82 to 1.01.
Homologues: Orthologues: chimpanzee POLR2B (100% identical), guinea pig POLR2B (100% identical), macaque POLR2B (100% identical), rat Polr2b (100% identical), dog POLR2B (99% identical), mouse Polr2b (99% identical), pig POLR2B (99% identical), rabbit POLR2B (99% identical), tropical clawed frog polr2b (99% identical), Drosophila melanogaster Polr2B (86% identical), Caenorhabditis elegans rpb-2 (79% identical), zebrafish polr2b (30% identical). Paralogues in human: POLR3B (38% identical), POLR1B (28% identical).
Diseases named in the same sentence as POLR2B in open-access papers:
POLR2B is named in the same sentence as 27 diseases in open-access papers, as found by Europe PMC text mining. Sharing a sentence is not in itself a finding about the gene and the disease. The quoted sentences say what the papers report.
glioma (2 papers, 2024 to 2025). A benign or malignant brain and spinal cord tumor that arises from glial cells (astrocytes, oligodendrocytes, ependymal cells). "In glioma stem cells (GSCs), circPOLR2B was discovered to form R-loops with its parental gene, POLR2B, in the nucleus." (PMID 40558832, 2025). "The YTHDC1/circPOLR2B/POLR2B/PBX1 axis plays a regulatory role in the biological behavior of GSCs, offering potential targets and novel strategies for the treatment of glioma." (PMID 39090090, 2024). "In glioma stem cells, elevated YTHDC1 expression enhanced the nuclear export of m6A-modified circPOLR2B, reducing the formation of R-loops in the nucleus with the parental POLR2B gene." (PMID 40558832, 2025).
3-M syndrome (1 paper, 2016). 3M syndrome is a primordial growth disorder characterized by low birth weight, reduced birth length, severe postnatal growth restriction, a spectrum of minor anomalies (including facial dysmorphism) and normal intelligence. "Biological pathways analysis showed that POLR2B protein could interact with OBSL1 protein, which was associated with one of the commonest primordial growth disorders, 3-M syndrome." (PMID 26884814, 2016).
age-related macular degeneration (1 paper, 2015). Age-related loss of vision in the central portion of the retina (macula), secondary to retinal degeneration. "We did not measure sight-impairment in our CC strains, however, a human GWAS of age-related macular degeneration identified a QTL at human chromosome 4q12 containing the following genes: REST, C4orf14, POLR2B and IGFBP733." (PMID 26548763, 2015).
chronic hepatitis B virus infection (1 paper, 2022). Chronic form of hepatitis B infection. "Chronic hepatitis B virus infection as an independent predictor of renal outcome in patients with type 2 diabetes mellitus also suggests an important role for POLR2B in DN." (PMID 36482994, 2022).
colorectal cancer (1 paper, 2021). A primary or metastatic malignant neoplasm that affects the colon or rectum. "We found that there were intensive protein-protein interaction pairs, and 3 potential hub genes (POLR2B, GNB2, and GNG2) were identified, which suggested that universal recurrence associated genes may cooperate together to have an impact on the recurrence of stage II colorectal cancer patients." (PMID 33628243, 2021).
diabetes (1 paper, 2022). "Because macular degeneration is closely related to diabetes, POLR2B may be involved in the process of diabetes." (PMID 36482994, 2022).
Eμ (1 paper, 2016). "Nevertheless, control shRNAs targeting essential genes (Rpa1, Rpa3 and Polr2b;) were consistently depleted in all four replicates, as were shRNAs targeting genes that either cooperated with Myc (Prmt5 and Odc) or belonged to known oncogenic pathways in Eμ-myc lymphomas (Adsl and Rsl24d1)." (PMID 27635472, 2016).
hepatocellular carcinoma (1 paper, 2024). A malignant tumor that arises from hepatocytes. "As the parental gene of circPOLR2B, POLR2B is highly expressed in hepatocellular carcinoma, and high POLR2B expression is positively correlated with poor prognoses in lung cancer patients." (PMID 39090090, 2024).
kidney damage (1 paper, 2021). "The other six markers, CDC5L, HNRNPU, NUDT21, PAPOLA, POLR2B, and WBP4, were all negatively correlated with GFR, indicating that these genes may aggravate kidney damage in patients with LN." (PMID 34557492, 2021).
macular degeneration (1 paper, 2022). Loss of vision in the central portion of the retina (macula), secondary to retinal degeneration. "POLR2B has been reported to be associated with macular degeneration at home and abroad." (PMID 36482994, 2022).
Mitochondrial myopathy (1 paper, 2024). "Thus, clear causality for POLR2B in this mitochondrial myopathy could not be established." (PMID 38998058, 2024).
thyroid cancer (1 paper, 2024). "We found a huge increase in the expression control of POLR2B in both the anaplastic (ΔREC = 485) and the papillary (ΔREC = 206) thyroid cancer cell lines, but not in the tumor (ΔREC = 5)." (PMID 38790250, 2024). "Thus, although, for the investigated thyroid tissue, both POLR2B and TAF6 might be used as housekeeping genes, they are not suitable as references for cultured thyroid cancer cells." (PMID 38790250, 2024).
tumor (6 papers, 2022 to 2025). "Another molecule, POLR2B, which helps control how genetic information is copied and used, has been linked to worse outcomes in kidney and other cancers, further emphasizing the role of gene regulation in tumor aggressiveness." (PMID 41514860, 2025). "Both, proapoptotic BCL-2 or MAP kinase pathway members (BIK, BAK1, MAP3K12, and MAPK9) and proliferation-associated tumor drivers (FOS, HOXA3, and POLR2B) had an increased gene expression." (PMID 35778418, 2022). "Knockdown of YTHDC1, POLR2B, and PBX1 reduced xenograft tumor volume and prolonged the survival of nude mice." (PMID 39090090, 2024). "It is interesting to note that POLR2B was up-regulated in both cell lines, but not in the tumor (x(T) = 1.15; x(Φ) = 74.40; x(Θ) = 80.06), while TAF6 was down-regulated in both cell lines, but not in the tumor (x(T) = −1.02; x(Φ) = −1.91; x(Θ) = −3.24)." (PMID 38790250, 2024). "In the tumor orthotopic transplantation experiment, the survival analysis of the nude mice showed that the individual knockdown of YTHDC1, POLR2B, or PBX1 could prolong survival." (PMID 39090090, 2024). "Unfortunately, romidepsin and T417 as tumor targeting drugs and targeting the YTHDC1/circPOLR2B/POLR2B/PBX1 axis were not examined in the present study." (PMID 39090090, 2024).
infection (2 papers, 2017 to 2020). The state of being infected such as from the introduction of a foreign agent such as serum, vaccine, antigenic substance or organism. "WT MHV68 infection reduced the levels of Pol II subunits Polr2a (Rpb1), Polr2b (Rpb2) and Gtf2B (TFIIB) beginning at 20 hpi." (PMID 32032393, 2020).
POLR2B also shares sentences with these, for which no sentence is quoted: cancer (4 papers); COVID-19 (1); disorder of glycosylation (1); endometrial cancer (1); Epstein-Barr virus infection (1); head and neck cancer (1); Huntington disease (1); lung carcinoma (1); lymphoma (1); pancreatic NET (1); somatostatinoma (1); type 2 diabetes mellitus (1); virus infection (1).